KLF4 (KLF transcription factor 4)
Diseases named in the same sentence as KLF4 in open-access papers (continued):
Sharing a sentence is not in itself a finding about the gene and the disease.
cancer (continued). "A handful of evidence supports KLF4’s involvement in regulating mitochondrial homeostasis in both healthy and cancer cells." (PMID 31245170, 2018). "Despite the pooling studies that corroborate KLF4’s unquestionable impact on mitochondrial function in normal and cancer cells, more research is needed to better gain mechanistic insights." (PMID 31245170, 2018). "A Cancer Stem Cell Transcription Factor Activation Array (Signosis, Inc, number FA-1004) also found KLF4, MYC, NANOG, OCT-3/4, SOX-2 and SNAIL activated in both MCF-7 and T47D after treatment with the CM of HA-BrC cells (data not shown)." (PMID 29928478, 2018). "Recently, KLF4 has gained much attention not only due to its multifaceted roles in normal and cancer cells, but also due to its key function as one of the four transcription factors required for induced pluripotency." (PMID 31245170, 2018). "We also tested the levels of KLF4α, which is a KLF4 isoform that was recently shown to antagonize the function of KLF4 and to stimulate cancer cell proliferation." (PMID 30555344, 2018). "Focusing on the presence of pluripotency markers thereafter, we observed increased gene expression of Krüppel-like factor 4 (Klf4) and N-myc, while Nestin, a putative marker of cancer stem cells, decreased." (PMID 30185144, 2018). "For the rest of the study, we chose the Dox dose 1 μg/ml, which induced KLF4 expression to a level (~20–27 fold) similar to that during cancer cell reprogramming when challenged by growth factors." (PMID 28553926, 2017). "In sum, our study provides new insights into the regulation of this cluster in development and cancer and opens up new opportunities for therapeutic intervention in tumors in which the KLF4-miR-182 cluster is deregulated." (PMID 28412746, 2017). "In cancer cells, Sox9 and Krüppel-like factor 4 (KLF4) interact with β-catenin and reduce its binding to TCF4 and showed anti-oncogenic activity by inhibiting the activity of the Wnt/β-catenin signaling pathway." (PMID 28279198, 2017). "Accumulating evidence determined that KLF4 is expressed at a low level and exerts a tumorsuppressive effect in many types of cancer." (PMID 28978114, 2017). "We found that not only the miR-145/c-Myc/PTBP1/PKMs axis, but also the novel miR-145/KLF4/PTBP1/PKMs cascade operated in the regulation of cancer energy metabolism." (PMID 28380435, 2017). "For example, Our previous studies indicate that treatment of cancer cells with hepatocyte growth factor induced cancer stem cell phenotypes by increasing the expression of reprograming factors including KLF4." (PMID 28553926, 2017). "In this study, a new mechanism of E-cadherin loss, which is mediated by down-regulated expression of Klf4 in NPC, is in line with the previous reports in various cancers." (PMID 29212199, 2017). "In the last half-decade many research groups employed iPSC technology in their research involving human cancer cells, mainly through the overexpression of Oct4, Sox2, Klf4, and c-Myc factors." (PMID 27766946, 2016). "Along with its recently identified role in Epstein Barr Virus reactivation during differentiation, our studies demonstrate the importance of KLF4 in the life cycles of multiple human cancer viruses." (PMID 27386862, 2016). "KLF4 has been found to be downregulated in many types of cancers, indicating its possible contribution to cellular hyperproliferation and malignant transformation." (PMID 27022622, 2016). "Forced expression of KLF4 profoundly attenuated lung cell proliferation and cancer formation in a murine model." (PMID 27153563, 2016). "In accordance with previous reports in cancer cells, we found that miR-103 represses the translation of KLF4 mRNA by direct interaction with a conserved binding site in its 3′UTR, which results in NF-κB-mediated upregulation of CXCL1 in ECs48." (PMID 26837267, 2016). "Here, we try to investigate KLF4 induced senescence in cancer cells and further decipher the molecular mechanisms of the KLF4-induced senescence." (PMID 27531889, 2016).
cancer (continued). "Two Stat3 signaling target genes, c-Myc and Klf4, play critical roles in cancer stem cell self-renewal." (PMID 27460364, 2016). "Taken together, these findings suggested that KLF4 suppressed cancer cell growth, migration and adhesion." (PMID 27153563, 2016). "As expected, hypoxic exposure significantly increased cancer stemness related factors (c-Myc, Klf4, Nanog, and Oct4) and Wnt/β-catenin signaling components (Wnt1, TCF4, and Cyclin D1)." (PMID 26965643, 2016). "miR-145 has been found to have roles in the pathogenesis of many different types of cancer and to be an important modulator of smooth muscle, in part through modulation of KLF4." (PMID 27907012, 2016). "Many evidence have shown that KLF4 expression is significantly reduce in a large number of human cancers including gastrointestinal, oesophageal, lung, pancreatic, colorectal, prostate, B-lymphocyte, and bladder cancers." (PMID 27105535, 2016). "When Oct4, Klf4, and c-Myc were overexpressed in a murine cancer cell line of melanoma, the generated iPCs were able to form viable chimeric mice after injection into blastocysts." (PMID 27766946, 2016). "Similar to our study on KLF4, it has been shown that splicing deregulation of KLF6 results in a specific variant, KLF6-v1, that is associated with an increased risk of various cancers and opposes KLF6(FL) effects." (PMID 27323810, 2016). "MiR-103 has a key role in regulating insulin sensitivity in adipocytes by targeting caveolin-1, and in cancer cell growth and metastasis by repressing different targets, including KLF4 (refs 48, 58, 59)." (PMID 26837267, 2016). "KLF4(FL) levels mostly paralleled those of KLF4 all, with the exception of the carcinoma patient 1 (right)." (PMID 27323810, 2016). "KLF4α/KLF4(FL) ratios were variable across the samples, but highest in the carcinoma patients, which was due to their elevated KLF4α." (PMID 27323810, 2016). "In fact, hypermethylation at KLF4 gene promoter and enhancer is documented in carcinomas of the colon, stomach, cervix and kidney." (PMID 26847634, 2016). "Since chromosomal deletion of KLF4 gene locus at 9q31.2 is a rare event in carcinomas, epigenetic inactivation of the gene is a prime candidate responsible for the loss of expression." (PMID 26847634, 2016). "Mounting evidence shows that KLF4 expression and activity is altered in a large number of human cancers, including gastric, colorectal, esophageal, prostate, lung, bladder, and B-lymphocyte cancers." (PMID 26517087, 2015). "The function of KLF4 is context-dependent, during cancer development and progression, and in different cancer types." (PMID 26517087, 2015). "Kruppel-like factor 4 (Klf4) is a transcription factor that regulates many important cellular processes in stem cell biology, cancer, and development." (PMID 26226504, 2015). "Consistent with this notion, γ-IR was reported to induce reprogramming of cancer stem cells that express the pluripotency genes Oct4, Sox2, Nanog, and Klf4 in a Notch-dependent manner for up to 5 days post-IR." (PMID 26528440, 2015). "Several miRNAs have been demonstrated to regulate stemness factors such as OCT4, NANOG, SOX2 and KLF4 in cancer cells, thereby modulating the proliferation, apoptosis, differentiation, drug resistance and immunity of cancer cells." (PMID 25603874, 2015). "miR-103a is shown to promote cancer-like properties by down-regulating KLF-4 and DAPK, but has also an interesting role in the modulation of miRNA processing and function via down-regulation of Dicer and miRNA binding Argonaute AGO1." (PMID 25822230, 2015).
cancer (continued). "With the exception of Myc (which was only present in a subset of benign, borderline, and malignant tumors), Oct4, Nanog, Sox2, and Klf4 were detectable at variable levels across both normal and diseased tissues." (PMID 26412983, 2015). "Accordingly, low levels of KLF4 mRNA or protein have been particularly encountered in cancers of different epithelia." (PMID 25181544, 2014). "Among 18 common predicted TFs for over-expressed mRNAs, Kruppel-Like Factor 4 (KLF4) located at PCSRs was found to be down-expressed in 7 types of cancers." (PMID 24796549, 2014). "We demonstrated that ALDH+ phenotypes exhibit cancer stem-like properties of enhanced invasion, colony formation ability, as well as increased expression of stem cell mediator KLF4." (PMID 25216266, 2014). "Another critical issue that limits the potential application of iPS technology is that all four transcription factors (Sox2, Oct4, Klf4, and c-Myc) are found to be frequently overexpressed in various cancers." (PMID 25116380, 2014). "IR has been shown to reprogram differentiated cancer cells into iBCSCs or liver CSCs through the re-expression or upexpression of the stemness genes Oct4/SOX2/Nanog/KLF4 and SOX2/OCT3/Oct4, respectively." (PMID 25003837, 2014). "Being a potent inhibitor of cell cycle progression, p21 seems to be intimately related to KLF4’s function; KLF4 and p21 are context-dependent opposing force in cancer." (PMID 25216266, 2014). "The KLF4 gene, a critical transcription regulator of cell growth and differentiation, has been reported to be dysregulated in several human cancers." (PMID 24551169, 2014). "Its role, especially in the context of cancer, has been extensively studied, and several studies have explored the role of KLF4 in vascular smooth muscle cell and vascular endothelial cell." (PMID 24079748, 2013). "As expected, the KLF4 was expressed in all tested cell lines and the mRNA levels and the protein levels in these cancer cell lines were significantly lower than the FHC cell line." (PMID 23418515, 2013). "These 58 predicted target mRNAs included many genes previously reported to be involved in tumorigenesis of CRC or other malignant tumors such as KLF4, SFRP1, SFRP2, RNF138." (PMID 22703586, 2012). "Further studies are in progress on the role of pluripotency factors, cancer stem markers, and other potential molecular targets of the miR-206/KLF4 axis." (PMID 23006636, 2012). "More recently, KLF4 has been shown to inhibit the migration and invasion activities in several cancer models, suggesting its potential role as a metastasis suppressor." (PMID 22937066, 2012). "Low-abundance miRNAs are worthy of further investigation, because their targets include KLF4 and other pluripotency and cancer stem-cell factors." (PMID 23006636, 2012). "Caco-2 cells exhibited low endogenous levels of both miR-206 and KLF4, similar to the non-cancer colon embryonic epithelial cell line CCD841 (solid black bar)." (PMID 23006636, 2012). "Recently, a KLF4/miR-206 autoregulatory feedback loop was reported to regulate protein translation reciprocally in normal and cancer cells." (PMID 23006636, 2012). "Our study shows that the expression of KLF4 in cancers was significantly lower than that in normal tissues." (PMID 21982273, 2011). "We divided carcinoma patients into three groups, either high KLF4 expression with Quick score of 9-12, moderate KLF4 expression with Quick score of 5-8, or weak KLF4 expression with Quick score of 1-4." (PMID 21978458, 2011). "In fact, a meta-analysis of publicly available gene expression data suggested that at least one of the four pluripotency factors Oct3/4, SOX2, Klf4, and c-myc is overexpressed in 18 out of 40 cancer types." (PMID 20814443, 2010).
cancer (continued). "The ectopic expression of c–Myc and Klf4 genes isthe most dangerous because of the high probability that malignant tumors will develop." (PMID 22649638, 2010). "Klf4 is downregulated in many human cancers including colorectal, gastric, bladder and adult T cell leukemia." (PMID 20514221, 2009). "Mechanistic studies indicate that promoter hypermethylation and hemizygous deletion contribute to KLF4 down-regulation in cancer." (PMID 20119532, 2009). "In addition to inhibiting the self‐proliferation and other functions of cancer cells, KLF4 can also enhance the sensitivity of cancer cells to chemotherapeutic drugs and radiotherapy, thereby improving treatment efficacy." (PMID 41532367, 2026). "Such bidirectional interactions could partly explain the dualistic nature of KLF4 in different cancer types." (PMID 41532367, 2026). "Moreover, KLF4 links cancer cells to MDSCs: alterations in cancer‐cell KLF4 expression modulate the production of chemokines such as CXCL5, thereby influencing MDSC recruitment into the TME." (PMID 41532367, 2026). "We conducted a comprehensive literature review to elucidate the expression patterns, regulatory mechanisms, and functional roles of KLF4 across different TME components, including cancer cells, immune cells, cancer‐associated fibroblasts, pericytes, and extracellular matrix." (PMID 41532367, 2026). "Moreover, we will present the implications of KLF4 regulation of myeloid cells in infection, wound healing, and cancer, and delve into the potential of KLF4 as a regulator in trained immunity." (PMID 40552304, 2025). "Previous studies have suggested that the opposing roles of KLF4 in cancer cells (suppressing vs. promoting) may derive from its subcellular localization." (PMID 40066228, 2025). "Future investigations utilizing long-read RNA sequencing, splice isoform-specific antibodies, or CRISPR-mediated isoform knockout may be necessary to dissect the role of individual KLF4 isoforms in immune cell plasticity and cancer stem cell behavior." (PMID 40552304, 2025). "A group reported that KLF4 is a hallmark of cytolytic effector-like CD8 T cells during the exhaustion process; therefore, ectopic KLF4 expression can enhance the activity of exhausted T cells and is associated with better prognosis in cancer patients." (PMID 40589762, 2025). "However, KLF4 also demonstrates oncogenic properties in HCC which are closely related to its cancer stem cell (CSC) maintenance capacity." (PMID 39995670, 2025). "The complex functions of KLF4 in cancer arise from its regulation across multiple molecular levels." (PMID 39995670, 2025). "The potential for bivalent chromatin at the KLF4 locus in stem-like immune or cancer cells is an intriguing but untested hypothesis." (PMID 40552304, 2025). "The role of KLF4 in cancer is complex and context-dependent." (PMID 40299916, 2025). "KLF4 is involved in the differentiation and polarization of monocytes and macrophages as part of the immune response after infection, in wound healing, and in cancer." (PMID 40552304, 2025). "Understanding this dual role could provide valuable insights into the precise role of KLF4 in cancer progression and its potential as a therapeutic target." (PMID 40299916, 2025). "Overall, this comprehensive investigation of KLF4 across multiple cancer types reveals its substantial clinical significance in terms of prognosis, protein expression, and immune cell infiltration in some cancers." (PMID 40299916, 2025). "KLF4’s role in the myeloid lineage is essential for numerous functions, such as differentiation, polarization, and responses to biological stressors, including immune responses to infection, wound healing, and cancer." (PMID 40552304, 2025). "Additionally, KLF4 is an IFN-γ target gene in cancer cell lines, with its function mediated by Stat1." (PMID 39995670, 2025).
cancer (continued). "In addition to its roles in cancer and trained immunity, KLF4, a Yamanaka factor, plays a central role in stem cell identity, and its expression is tightly epigenetically regulated, and it has been shown to promote the maintenance of pluripotency in iPSCs." (PMID 40552304, 2025). "Therefore, in this study, we employed a pan-cancer approach to identify alterations in KLF4 DNA sequence, gene and protein expression, and DNA methylation in more than 30 tumors." (PMID 40299916, 2025). "KLF4 has been shown to inhibit cell growth in various cancers." (PMID 40299916, 2025). "KLF4 also promotes cancer development through its regulation of MDSC differentiation and function." (PMID 40552304, 2025). "In addition to c-MYC, other pluripotency factors such as OCT4, SOX2, NANOG, and KLF4 are known to act as potent cancer drivers." (PMID 40541178, 2025). "Targeting both Nrf2 and KLF4 may, therefore, represent a promising therapeutic strategy to eliminate arsenic‐induced cancer stem‐like cells." (PMID 40755294, 2025). "Moreover, KLF4 can sensitize cancer cells to several established therapies, including cisplatin, cetuximab, mesalazine, and gefitinib, suggesting the potential for combinatory use with other anticancer drugs in future clinical trials." (PMID 39995670, 2025). "The inability of ORP100S to boost KLF4 in cancer cells could be related to the previously‐reported inability of Cys35 TRX mutants to stimulate proliferation in cancer cells, as well as differences in uptake or cancer cells’ altered signaling environment." (PMID 40932638, 2025). "The first is “miRNA and KLF4 and cancer” and is limited to the last 5 years." (PMID 40863723, 2025). "The analysis displayed in the GEO database indicated that the expressions of the Warburg effect key enzyme PKM2, CSC reprogramming factors OCT4 and KLF4 and cancer stemness marker CD44 in HBV(+) HCC were higher than those of HBV(−) HCC, with statistical significance, p < 0.05." (PMID 40717222, 2025). "Furthermore, even if reprogramming with only Oct4 and Klf4 can be successful in human cells, the remaining two factors related to cancer development still exhibit overexpression." (PMID 38699229, 2024). "KLF4 was positively correlated with cancer stemness in a variety of cancers, including HNSCC." (PMID 38916835, 2024). "KLF4 is a miR-7 target gene and in vivo studies report miR-7 inhibits the expression of KLF4 downregulating the proliferation, invasion, and transmigration of brain-tropic cancer stem cells (CSCs)." (PMID 39175471, 2024). "Overall, KLF4 emerges as a crucial target in the fight against cancer." (PMID 39135777, 2024). "Notably, 74 of these genes overlapped with well-known cancer-associated genes (CAGs), such as CCR4, KLF4, FANCG, and NAB2." (PMID 39267784, 2024). "One study showed that hypoxia can induce an embryonic-stem-cell-like transcriptional program, including the iPSC inducers Oct4, Sox2, c-Myc, Klf4, Nanog, and microRNA-302, in 11 cancer cell lines from the prostate, brain, kidneys, cervix, lungs, colon, liver, and breasts." (PMID 38891103, 2024). "A large variety of human cancers express high levels of c-Myc and Klf4." (PMID 38891103, 2024). "KLF4 plays a role in different types of cancer as oncogenic or anticancer factor." (PMID 38561775, 2024). "Furthermore, it significantly reduced the migratory and invasive capabilities of cancer cells by upregulating the expression of KLF4 at the protein level." (PMID 39335919, 2024). "KLF4 expression in the cancer group is significantly higher than that in the control group, and the positive rate of stage II, III and IV is higher than that of stage I. Its expression is independent of age and sex of patients, and is a potential biomarker in late stage of SCLC." (PMID 38560274, 2024). "Moreover, EI intervention resulted in a marked upregulation of the mRNA expression levels of the cancer stem cell markers, KLF4 and OCT4, within both MCF-7 and MCF-7PR cell lines." (PMID 38918989, 2024).